RN7SL610P (RNA, 7SL, cytoplasmic 610, pseudogene)
Gene: Miscellaneous RNA gene on chromosome 2 (23,996,795 to 23,997,085, reverse strand). Ensembl gene ENSG00000243847.
Homologues: Orthologues: chimpanzee Metazoa_SRP (95% identical). Paralogues in human: RN7SL2 (83% identical), RN7SL1 (82% identical), RN7SL3 (80% identical), RN7SL326P (80% identical), RN7SL431P (79% identical), RN7SL492P (78% identical), Metazoa_SRP (78% identical), RN7SL543P (78% identical), RN7SL627P (78% identical), RN7SL664P (78% identical), RN7SL788P (78% identical), RN7SL300P (78% identical), and 702 more.